ENSG00000296557 (novel transcript)
Gene: Long non-coding RNA gene on chromosome 7 (76,292,029 to 76,302,665, forward strand). Ensembl gene ENSG00000296557.
Gene Ontology:
Biological process: SRP-dependent cotranslational protein targeting to membrane, signal sequence recognition
Cellular component: signal recognition particle, endoplasmic reticulum targeting